MPO (myeloperoxidase)
Diseases named in the same sentence as MPO in open-access papers (continued):
Sharing a sentence is not in itself a finding about the gene and the disease.
glomerulonephritis (continued). "Furthermore, several forms of glomerulonephritis have shown that endogenous MPO, secreted by neutrophils, can suppress dendritic cells and T cell function." (PMID 34899751, 2021). "To determine if the loss of tolerance to MPO induced by S. aureus JH1-derived pSJH101 6PGD391–410 could result in anti-MPO glomerulonephritis, we used our established model of T-cell-mediated anti-MPO glomerulonephritis." (PMID 31358739, 2019). "Likewise, direct injection of MPO during a model of anti-MPO glomerulonephritis induced significant IL-17A production and development of an MPO-specific DTH response as well as renal disease." (PMID 30983883, 2019). "It is characterized by autoantibodies directed against neutrophil proteins myeloperoxidase (MPO) and proteinase-3 (PR3) and is associated clinically with rapidly progressive glomerulonephritis and inflammatory necrosis of small blood vessels in lungs, skin, and other organs." (PMID 31781107, 2019). "These include lack of injury in Mpo-/- mice or OVA immunised mice, a similar degree of injury in B cell deficient mice and the induction of glomerulonephritis by transfer of MPO-specific, but not OVA-specific CD4+ T cell clones." (PMID 29315316, 2018). "There is one reported case of both MPO-ANCA and anti-PLA2R antibody positivity in the serum, and serum anti-PLA2R antibodies and glomerular deposits were simultaneously detected in some patients with ANCA-associated glomerulonephritis combined with MN." (PMID 29792176, 2018). "The anti-neutrophil cytoplasmic antibody (ANCA) associated vasculitides (AAV) are diseases in which autoimmunity to the neutrophil granule proteins myeloperoxidase (MPO) or proteinase-3 (Pr3) can cause multi-organ injury, including rapidly progressive glomerulonephritis." (PMID 29315316, 2018). "Similarly, C5aR1 is expressed scarcely, whereas expression of C5aR2 is upregulated in MPO-ANCA+ glomerulonephritis." (PMID 29686675, 2018). "However, in the murine model of MPO-ANCA-induced glomerulonephritis, blocking of C5aR1 with a small molecule antagonist (avacopan) is protective, whereas lack of C5aR2 lead to aggravated disease." (PMID 29686675, 2018). "A mouse model mimicking glomerulonephritis seen in human ANCA-associated vasculitis has been developed in which mice are immunized with MPO followed by passive transfer of low dose anti-glomerular basement membrane antibodies, which then induces focal segmental glomerulonephritis." (PMID 28878769, 2017). "Unilateral vocal cord paralysis without other symptoms or signs, but with positive perinuclear anti-neutrophil cytoplasmic antibodies (ANCA) and anti-myeloperoxidase autoantibodies, followed an unfavorable course months later with rapidly progressive glomerulonephritis." (PMID 28559644, 2017). "Furthermore, animal models have shown that MPO antibodies and anti-MPO specific T-cells can induce a crescentic glomerulonephritis and lung disease." (PMID 26552432, 2015). "The two major antigens for ANCA, proteinase 3 (PR3) and myeloperoxidase (MPO), are usually referred to as the serological markers of ANCA-associated vasculitis and glomerulonephritis on ELISA tests, with perinuclear and cytoplasmic lesions in neutrophils, respectively." (PMID 25648906, 2015). "Compared with AAV-associated typical glomerulonephritis, isolated interstitial nephritis AAV cases presented with much less severity and demonstrated significantly fewer urinary red blood cells, lesser 24-hour urine protein, and lower levels of serum creatinine and serum MPO titers." (PMID 39803122, 2024). "Moreover, AAV-associated interstitial nephritis without glomerulonephritis tended to exhibit lower levels of sCr, 24hUP, and MPO titers with no significance." (PMID 35759125, 2022).
glomerulonephritis (continued). "Several animal experiments have demonstrated that MPO-ANCA might be a directly pathogenic autoantibody involved in MPA pathogenesis, thus indicating that MPO-ANCA could be sufficient to cause pulmonary capillaritis and glomerulonephritis in certain biological environments." (PMID 36210838, 2022). "Among the four double-positive patients with relapse, who were positive for both MPO-ANCA and PR3-ANCA at diagnosis, two experienced both glomerulonephritis (GN) and interstitial lung disease (ILD) recurrence, and the remaining two had only ILD recurrence." (PMID 41601767, 2026). "EGPA is characterized by eosinophil-rich granulomatous inflammation, asthma, eosinophilia, and MPO-ANCA positivity, especially with glomerulonephritis." (PMID 41376741, 2025). "Humoral axis: MPO-ANCA identifies the vasculitic endotype and correlates with glomerulonephritis and neuropathy, though titers are imperfect for activity monitoring." (PMID 41303621, 2025). "The presence of anti-MPO ANCA, confined mainly to the vasculitic endotype, supports an autoantibody-mediated component responsible for glomerulonephritis, neuropathy, and purpura." (PMID 41303621, 2025). "Here, we report the case of a young female with double positivity for MPO-ANCA and anti-GBM antibodies who developed end-stage renal disease due to rapidly progressive glomerulonephritis." (PMID 41209892, 2025). "Co-localization of DNA, MPO, and PR3 in renal tissue from patients with small vessel vasculitis (SVV) glomerulonephritis suggests the presence of NET and ANCA antigens in inflamed tissue and MPO-ANCA in serum." (PMID 38672433, 2024). "We used the Medical Subject Headings (MeSH) terms and keywords related to “COVID-19 vaccine,” “glomerulonephritis,” “p-ANCA,” and “MPO-ANCA” with the date of inception to March 5, 2024." (PMID 38817489, 2024). "Kidney biopsy revealed pauci-immune glomerulonephritis, and serum was positive for ANCA along with myeloperoxidase antibody." (PMID 37388719, 2023). "Colocalization of DNA, MPO and PR3 in kidney tissue of small-vessel vasculitis (SVV) glomerulonephritis patients, for example, indicates the presence of NETs and ANCA antigens in inflamed tissue." (PMID 32276504, 2020). "The combination of anti-histone antibody, very high titer of MPO and/or PR3 ANCA, and pauci-immune glomerulonephritis, support the diagnosis of hydralazine-induced ANCA-associated vasculitis in the appropriate clinical setting." (PMID 32290867, 2020). "Pulmonary lesions were occasionally and inconsistently detected after transfer of MPO peptide-specific CD4+ T cell clones, despite all mice developing glomerulonephritis." (PMID 32373109, 2020). "Finally, MPO-specific effector CD4 T cells migrate to inflamed glomeruli where they recognise MPO and direct accumulation of macrophages and fibrin, causing, together with ANCA-induced neutrophil responses, severe and proliferative renal vasculitis (glomerulonephritis; GN)." (PMID 26904693, 2016). "A high titer of anti-myeloperoxidase ANCA was found, and a renal biopsy revealed necrotizing crescentic pauci-immune glomerulonephritis." (PMID 26502884, 2015). "This case describes a patient with hydralazine-induced ANCA who presented with pauci-immune glomerulonephritis and the simultaneous presence of multiple autoantibodies (ANAs, anti-histone antibodies, and P-ANCA positive with anti-MPO and anti-PR3)." (PMID 25525550, 2014). "H&E staining of kidney sections clearly showed glomerulonephritis from splenocytes derived from rmMPO immunized MPO–/– mice but not from splenocytes derived from immunized WT mice." (PMID 40020049, 2025). "Anti-IL17A treatment did not impact development of anti-MPO antibodies, onset of glomerulonephritis or pulmonary vasculitis." (PMID 40821760, 2025).
glomerulonephritis (continued). "However, cases such as this, in which MPO-ANCA and anti-GBM antibodies are simultaneously positive, have been suggested to have a higher recurrence rate of glomerulonephritis and worse renal prognosis than cases in which only anti-GBM antibodies are positive." (PMID 41209892, 2025). "Here, we report a case of acute interstitial nephritis (AIN) as the sole renal lesion in myeloperoxidase (MPO) AAV without glomerulonephritis." (PMID 39803122, 2024). "Workup revealed elevated anti-myeloperoxidase antibody (MPO-AB) and perinuclear ANCA (p-ANCA) antibodies with a biopsy confirming focal cresenteric glomerulonephritis, and the patient was initiated on steroid therapy with notable improvement and a return to baseline kidney function." (PMID 37214004, 2023). "MPO and PR3-ANCA glomerulonephritis (GN) differ notably in their histopathological presentation." (PMID 36294902, 2022). "Though AAV displays a slight overall male predominance, renal involvement is more often present in females, which may be explained by the female predominance of MPO-AAV and its higher incidence with glomerulonephritis." (PMID 35721093, 2022). "In contrast, it has been shown that antibodies against PR3 and MPO induce NET formation in vitro, and this is controlled by regulated necrosis such as necroptosis of glomerular neutrophils, eventually contributing to MPO-ANCA-mediated glomerulonephritis." (PMID 34204207, 2021). "We present a case of acute interstitial nephritis (AIN) as the sole renal lesion without glomerulonephritis with myeloperoxidase (MPO) AAV." (PMID 31346511, 2019). "In this model, C57BL/6 mice immunized with MPO lose tolerance to MPO but do not develop ANCA of sufficient pathogenicity to induce glomerulonephritis." (PMID 31358739, 2019). "We used the model of experimental autoimmune anti-MPO glomerulonephritis to model these processes and found that absence of C3aR did not affect albuminuria, histological injury or glomerular leucocyte influx." (PMID 29315316, 2018). "Importantly, splenocytes from HA-rmMPO–immunized MPO–/– mice but not WT mice also induced glomerulonephritis." (PMID 40020049, 2025). "(5-15% mice in wild-type, 80% mice in RAG2-deficient) MPO-ANCA passive transfer into mice lacking C4, which is required for activation of the classical pathway and the lectin pathway of the complement pathway, developed glomerulonephritis as in the wild type." (PMID 35812453, 2022). "However, in other forms of glomerulonephritis where MPO is not an autoantigen (including antiglomerular basement membrane GN and pristine-induced lupus nephritis), endogenous MPO suppresses T cell responses." (PMID 30983883, 2019). "However, the common histological findings of the present patients with no history of drug abuse, i.e., both MPO and PLA2R in glomerular deposits, suggested that the coexistence of ANCA-associated glomerulonephritis and MN-lesions reflected mutually related diseases rather than a coincidence." (PMID 29792176, 2018). "Although myeloperoxidase (MPO)-ANCA was not completely eliminated, its levels were significantly reduced and demonstrated a strong protective effect against autoantibody-induced glomerulonephritis." (PMID 39734406, 2024). "These cases did not develop anti-GBM glomerulonephritis and the anti-GBM findings were considered false positives in these anti-MPO positive patients." (PMID 30348108, 2018). "In our retrospective study, 57% of MPO-ANCA ILD patients had renal involvement and 50% of those without initial renal involvement developed glomerulonephritis diagnosed at a median time of 3.2 years after the onset of pulmonary symptoms, with a maximum interval of 10 years." (PMID 38445024, 2024). "In addition, no vasculitic lesion was observed in the mouse models with MPO-ANCA production, whereas WKY rats with MPO-ANCA developed pulmonary capillaritis and glomerulonephritis." (PMID 27375623, 2016).
glomerulonephritis (continued). "Furthermore, while LAMP2 showed no homology with MPO or PR3 (thus excluding synergy with the anti-idiotype hypothesis), it showed significant similarity to the sequence of the bacterial protein FimH, which could induce both LAMP2-IgG and a pauci-immune glomerulonephritis on immunisation of WKY rats." (PMID 25056155, 2014).
endothelial dysfunction (148 papers, 2007 to 2026). In vascular diseases, endothelial dysfunction is a systemic pathological state of the endothelium (the inner lining of blood vessels) and can be broadly defined as an imbalance between vasodilating and vasoconstricting substances produced by (or acting on) the endothelium. "The involvement of MPO in the development of endothelial dysfunction is linked to its competency to oxidize polyunsaturated lipids, leading to the formation of reactive aldehydes, including malondialdehyde (MDA)." (PMID 41226326, 2025). "The present review provides essential information on the pathological relevance of MPO in endothelial dysfunction and CVD risk in PLWH." (PMID 41226326, 2025). "PE shares metabolic risk factors with CVD, such as endothelial dysfunction and inflammation, and elevated levels of MPO are linked to poor prognosis and increased risk of CVD-related mortality." (PMID 40806204, 2025). "Myeloperoxidase (MPO), an oxidative stress biomarker released by activated neutrophils, has been implicated in endothelial dysfunction, lipid peroxidation, and microvascular thrombosis." (PMID 40710793, 2025). "MPO levels correlate with body weight and endothelial dysfunction, while MPO deficiency reduces PVAT inflammation, promotes adipocyte “beiging” via sGC-β1, increases adiponectin secretion, and improves vascular function." (PMID 40252642, 2025). "Elevated MPO levels are associated with an increased risk of cardiovascular disease, as they contribute to endothelial dysfunction and plaque instability, making MPO a vital biomarker in all phases of endothelial pathology." (PMID 40244022, 2025). "For instance, in humans, plasma MPO levels have been found to positively correlate with endothelial dysfunction and cardiovascular disease risk in individuals with T2D." (PMID 39769394, 2024). "As such, the role of MPO as a pathogenic mediator of endothelial dysfunction is an important question that needs to be investigated." (PMID 39456241, 2024). "MPO gene-deficiency also protected against endothelial dysfunction when apoE knockout mice were fed a high-fat diet for 8 weeks." (PMID 39061857, 2024). "Elevated MPO levels in plasma are associated with adverse cardiovascular events, including future risk of coronary artery disease, endothelial dysfunction, and MI in humans." (PMID 36982778, 2023). "Myeloperoxidase derived from monocytes and macrophages produces HOCl, which can induce tissue damage and is implicated in the pathogenesis of endothelial dysfunction." (PMID 37299525, 2023). "Despite an established role of VV and VP in the development of vascular inflammation and atherosclerosis, the quantitative associations among VV, MPO+ clusters, and IH have been unclear to date, particularly in the context of endothelial dysfunction." (PMID 36293013, 2022). "We found that the amounts of VV and MPO+ clusters were strongly correlated; further, MPO+ clusters density was significantly associated with balloon-induced IH and increased at calciprotein particle-provoked endothelial dysfunction." (PMID 36293013, 2022). "Third, recent evidence demonstrated that acute and severe hypouricemia induced in healthy individuals causes endothelial dysfunction, reduces blood pressure, decreases myeloperoxidase activity and increases lipid peroxidation." (PMID 34127048, 2021). "Activated neutrophils infiltrate the maternal systemic vasculature and release substances such as ROS, TNF-α and myeloperoxidase (MPO), causing endothelial dysfunction." (PMID 33013837, 2020). "Myeloperoxidase function have been implicated in endothelial dysfunction and vascular damage in the context of cardiovascular and kidney diseases." (PMID 31611761, 2019). "Neutrophil-derived enzymes, such as elastase and myeloperoxidase (MPO) and reactive oxygen species (ROS) contribute to tissue injury and endothelial dysfunction, predisposing patients to organ injury." (PMID 29234042, 2017).
endothelial dysfunction (continued). "Endothelial dysfunction is apparently a feature frequently seen in FD and appears to be closely linked to elevated levels of myeloperoxidase, excessive production of ROS and endothelial nitric oxide synthase uncoupling." (PMID 27835692, 2016). "Subendothelial accumulated MPO can act locally as an NO oxidase, inhibiting NO function and causing endothelial dysfunction." (PMID 24594096, 2014). "Alternatively, others observed that 4-years of exposure to NNRTI or PI-based HAART appears to be associated with reduced circulating levels of MPO and endothelial dysfunction markers such as sICAM-1 and sVCAM-1 in PLWH, comparable to those observed in HIV-negative persons." (PMID 41226326, 2025). "Similarly, in obese rat models, increased MPO activity has been linked to endothelial dysfunction and microvascular disorders, while MPO inhibition has improved endothelial function and reduced inflammation." (PMID 40900465, 2025). "The initial report indicated that NRTI, NNRTI, INSTI or protease inhibitor-based HAART exposure for at least three years was associated with raised levels of MPO that are consistent with increased markers of endothelial dysfunction, such as sE-selectin, sICAM-1, and sVCAM-1 in PLWH." (PMID 41226326, 2025). "These oxidative changes, which are facilitated by enzyme activities such as myeloperoxidase and lipoprotein-associated phospholipase A2, promote endothelial dysfunction and local vascular inflammation, thereby also enhancing foam cell formation and atherosclerotic plaque progression." (PMID 40649729, 2025). "Thus, sustained activation of MPO has been implicated in various inflammatory diseases, including endothelial dysfunction and atherosclerosis, highlighting its complex involvement in host defense and pathological processes." (PMID 41226326, 2025). "MPO also has many properties associated with cardiovascular disease, such as effects on apoptosis, NETosis, neutrophil migration and activation, platelet function, adaptive immunity, endothelial dysfunction, vascular function and leukocyte recruitment." (PMID 39087342, 2024). "MPO can be localized on the surface of endothelial cells and internalized, oxidizing NO and limiting its bioavailability, causing impaired endothelium-dependent diastole and resulting in endothelial dysfunction." (PMID 38275657, 2024). "In this study, we evaluate whether patient-derived ECFCs demonstrate their own reservoir of MPO that may contribute to mitochondrially-associated endothelial dysfunction and CAD in a unique CTCA-characterised cohort and biobank." (PMID 39456241, 2024). "MPO causes endothelial dysfunction, which could promote thrombosis, and it is possible that this explains the protection seen, rather than a mechanism that would be of benefit in other forms of crescentic glomerulonephritis." (PMID 36154801, 2023). "Studies have shown the associations between increased levels of MPO and endothelial dysfunction, because the oxidative interaction of MPO with circulating lipid components and vascular wall tissues seems to have a role in triggering the atherosclerotic process." (PMID 36678185, 2023). "Here, we employed two animal models and a clinical scenario to investigate which quantitative features (number, area, or density) of VV and MPO+ clusters are associated with IH and whether endothelial dysfunction affects the expansion of VV and MPO+ clusters." (PMID 36293013, 2022). "MPO binds strongly to the vascular endothelium through its interactions with the negatively charged glycocalyx in other chronic inflammatory diseases, including heart disease, to cause endothelial dysfunction." (PMID 35331340, 2022). "Effector mediators in NETs, including multiple proteinases and the pro-oxidant enzyme- myeloperoxidase, have been demonstrated to be causal factors for media destruction and endothelial dysfunction, and hence may also exacerbate coronary artery ectasia." (PMID 32122307, 2020).